SALL1 (spalt like transcription factor 1)
Diseases named in the same sentence as SALL1 in open-access papers (continued):
Sharing a sentence is not in itself a finding about the gene and the disease.
breast carcinoma (continued). "We next performed complementary in vivo studies, using murine breast cancer E0771 cells in humanized NOD-scid IL2Rγnull (NSG) mouse models, and explored whether SALL1 functions as a tumor suppressor for the tumorigenesis and metastasis of breast cancer in vivo." (PMID 29625565, 2018). "However, overexpression of SALL1 in cancer cells did not induce increased apoptosis or cell death in breast cancer cell lines." (PMID 29625565, 2018). "However, we did not observe changes of these two oncogenes in breast cancer cells mediated by SALL1 over-expression (Data not shown)." (PMID 29625565, 2018). "Unlike SALL1 and SALL2, studies showed higher SALL4 expression in breast cancer cell lines and primary tissues than their non-tumoral counterparts." (PMID 34944911, 2021). "SALL1 was transfected into human and murine breast cancer cell lines MDA-MB-231 (TNBC), MCF7 and E0771 (basal-like) (all with no or minor expression of SALL1) for the gain-of-function studies." (PMID 29625565, 2018). "(A) Transfection of SALL1, but not SALL4 in MCF-7 and E0771 breast cancer cells significantly induced the increased SA-β-Gal+ cell populations." (PMID 29625565, 2018).
glioma (5 papers, 2021 to 2026). A benign or malignant brain and spinal cord tumor that arises from glial cells (astrocytes, oligodendrocytes, ependymal cells). "Sall1 (Spalt-Like Transcription Factor 1), which is expressed specifically in microglia and is associated with microglial activation, suppresses glioma cell proliferation and migration and may work as a functional tumor suppressor gene in glioma." (PMID 35474103, 2022). "LncRNA PART1 can suppress glioma proliferation and migration via miR-374b/SALL1 axis, LINC00689 can inhibit glioma tumorigenesis via the miR-526b-3p/IGF2BP1 axis, GAS5 can alter the EMT process, proliferation, migration, and invasion of glioma cells through miR-106b targeting PTEN." (PMID 36425564, 2022).
Papillorenal syndrome (5 papers, 2018 to 2025). "Some of these are included in complex clinical syndromes such as branchio-oto-renal syndrome (EYA1, SIX1), renal-coloboma syndrome (PAX2), renal cysts and diabetes syndrome (TCF2/HNF1B) and Townes–Brocks syndrome (SALL1)." (PMID 28647851, 2018).
anal stenosis (4 papers, 2018 to 2024). "Autosomal dominant TBS1 is characterized by the triad of imperforate anus or anal stenosis in 84%, dysplastic ears in 87%, and thumb malformations in 89%, and is caused by variants in the SALL1 (spalt like transcription factor 1) gene." (PMID 36066768, 2023). "In the DECIPHER database, a 10.71 kb SALL1 deletion was reported in a patient with bilateral sensorineural hearing impairment, anal stenosis, broad fingertips, mild global developmental delay, and penile hypospadias." (PMID 36833185, 2023). "Overall, among the ten patients with SALL1 deletions, seven had an imperforate anus or anal stenosis and two had a ventrally positioned anus." (PMID 36833185, 2023). "Moreover, Sall4+/−; Sall1+/− mice exhibit renal agenesis and anal stenosis, demonstrating genetic interactions between Sall genes." (PMID 38345319, 2024).
deafness (4 papers, 2020 to 2025). An inherited or acquired condition characterized by the complete loss of the ability to hear from one or both ears. "Here, we found a significantly higher prevalence of deafness, dysplastic ear and thumb malformations when the SALL1 variant is located downstream of the glutamine-rich region in patients who were significantly younger (more missing data on age in this group), whereas deafness occurs with age." (PMID 40348827, 2025). "We identified five predicted highly suspected deafness-associated genes, namely, COL1A1, GJC3, RRM2B, SALL4 and SALL1, in the available databases, including Ensemble and OMIM, indicating that they were correctly identified as deafness-associated genes." (PMID 36803022, 2023).
hearing loss (4 papers, 2021 to 2024). "Among the 163 upregulated genes, we did not observe a clear enrichment of Gene Ontology processes but did obtain significant enrichment of genes associated with hearing loss, including the upregulation of Otof, Tectb, Cldn11, Sall1, Cldn14, Chrna10, Esprn, and Fgfr3." (PMID 38564333, 2024). "Site-specific mutations in COL1A1, GJC3, RRM2B, SALL4, and SALL1 cause otosclerosis ([MIM:120150]), delayed hearing sensitivity ([MIM:611925]), sensorineural deafness ([MIM: 604712]), hearing loss ([MIM:607343]) and ear dysplasia ([MIM:602218]), among other deafness-related disorders." (PMID 36803022, 2023).
prostate carcinoma (4 papers, 2010 to 2021). A carcinoma that arises from epithelial cells of the prostate gland. "For instance, Sall1 was found to be a potential target of the oncogenic miR-4286 in prostate cancer whereby miR-4286 knockdown abrogated Sall1’s ability to induce apoptosis and inhibit proliferation." (PMID 34195082, 2021). "Prostate cancer cell line PC-3 (low SALL1 expression) and melanoma cell line B16F0 (high SALL1 expression), as well as normal breast cell line MCF12A cells were included as controls." (PMID 29625565, 2018). "In parallel, SALL1 expression in cancer cell lines from other types of cancers (melanoma, prostate cancer, colon cancer and lymphoma), as well as in normal breast primary cell lines, fibroblasts and 293 T cells were also determined." (PMID 29625565, 2018). "Further, miR-4286 may exert its tumor-promoting actions, in part, by downmodulating SALL1 in prostate cancer (PCa)." (PMID 34257535, 2021). "(A) and (B) Transfection of SALL1 but not SALL4 significantly inhibited prostate cancer PC3 cell growth and proliferation." (PMID 29625565, 2018). "In addition we found that EMILIN2, FBLN2 and SALL1 were also frequently methylated in other common epithelial cancers, EMILIN2 and SALL1 in colorectal cancer and FBLN2 in prostate cancer." (PMID 20205715, 2010). "In addition, EMILIN2 and SALL1 also show frequent methylation in colorectal cancer and FBLN2 shows frequent tumour-specific methylation in prostate cancer." (PMID 20205715, 2010).
renal agenesis (4 papers, 2010 to 2024). Renal agenesis (RA) is a form of renal tract malformation characterized by the complete absence of development of one or both kidneys (unilateral RA or bilateral RA respectively), accompanied by absent ureter(s). "The Ifng GOF mutant kidneys do exhibit a phenotype reminiscent of the kidneys from the Sall1 loss-of-function mouse, which also shows renal agenesis or dysplasia." (PMID 29771971, 2018). "Homozygous Sall1-deficient mice present with renal agenesis at birth, and heterozygotes are normal." (PMID 23069192, 2013). "Taken together, these results suggest that an MM-specific increase in Ifng may cause renal agenesis or hypoplasia by regulating Sall1 expression, which is critical for the survival of renal progenitors, UB invasion, branching morphogenesis, and maintenance of multipotent renal progenitors." (PMID 29771971, 2018). "Therefore, aberrant increased Ifng expression in the developing embryo, as part of an innate immune response possibly initiated by a transplacental infection, may contribute to renal agenesis or hypoplasia by regulating the renal progenitor pool through Sall1 modulation." (PMID 29771971, 2018).
acute lymphocytic leukemia (3 papers, 2010 to 2021). "Two independent genome-wide analyses confirmed the hypermethylation of the aberrant SALL1 promoter in human samples of acute lymphocytic leukemia (ALL) and chronic lymphocytic leukemia (CLL)." (PMID 34944911, 2021). "SALL1 hypermethylation has been described in several malignancies, including non-small cell lung cancer, prostate tumors, chronic lymphocytic leukemia, and acute lymphoblastic leukemia." (PMID 28616099, 2017). "SALL1 was recently demonstrated to be hypermethylated in acute lymphocytic leukemia." (PMID 20205715, 2010).
chronic kidney disease (3 papers, 2018 to 2025). Impairment of the renal function secondary to chronic kidney damage persisting for three or more months. "Such regulation also matters in mammals, e.g., for the MSL2 targets Six1-4 or Sall1, whose haploinsufficiency causes syndromes associated with hearing loss, chronic renal failure, limb, and ear anomalies in humans." (PMID 30194291, 2018). "Consequently, comprehensive genetic analysis using next-generation sequencing (NGS) can identify SALL1 variants in patients with non-syndromic CAKUT or chronic kidney disease (CKD) of unknown etiology." (PMID 40658219, 2025).
colon cancer (3 papers, 2015 to 2025). "Intriguingly, SALL1 is downregulated in colon cancer, whereas SALL4 is overexpressed in it." (PMID 40869218, 2025).
developmental delay (3 papers, 2023 to 2025). "Although SALL1 is expressed in the cerebrum, intellectual disability and developmental delay are uncommon in SALL1-related disorders." (PMID 40658219, 2025). "We previously reported two patients with a deletion of the SALL1 gene confirmed by aCGH, both of whom exhibited developmental delays." (PMID 40658219, 2025).
leukemia (3 papers, 2010 to 2021). A malignant (clonal) hematologic disorder, involving hematopoietic stem cells and characterized by the presence of primitive or atypical myeloid or lymphoid cells in the bone marrow and the blood. "We showed that SALL1 inhibition was associated with inferior leukemia engraftment and prolonged survival compared to GFP- xenografted control cells." (PMID 29484122, 2018). "When sacrificed after 6 months, sh-SALL1 MV4-11 were found to be engrafted with CD45+ human cells yet they remained leukemia free." (PMID 29484122, 2018). "Identifying the SALL1 isoform deregulated in ALL and CLL could help define the role and mechanisms of SALL1 in leukemia." (PMID 34944911, 2021). "SALL1 mRNA was expressed in leukemia cells and cell lines at a much higher level than in NBM." (PMID 29484122, 2018). "Thus, depending on the hematological malignancy, SALL1 could play different roles, as a tumor suppressor in lymphoid progenitor-derived leukemia (ALL-CLL) and as an oncogene in myeloid progenitor-derived leukemia (AML)." (PMID 34944911, 2021). "Together, these studies suggest that SALL1 and SALL2 play opposite roles in myeloid progenitor-derived leukemia, as oncogene and tumor suppressor, respectively." (PMID 34944911, 2021). "However, in lymphoid progenitor-derived leukemia (ALL-CLL), SALL1 could act as a tumor suppressor." (PMID 34944911, 2021).
ovarian carcinoma (3 papers, 2010 to 2020). A malignant neoplasm originating from the surface ovarian epithelium. "SALL1 resides at 16q12.1- a region demonstrated to undergo loss of heterozygosity (LOH) in breast, prostate, ovarian cancer and in retinoblastoma." (PMID 20205715, 2010). "In addition, studies from other groups have demonstrated that SALL1, which is located at 16q12.1 is a region that was shown to undergo loss of heterozygosity (LOH) in breast, prostate, ovarian cancers and in retinoblastoma." (PMID 29625565, 2018).
renal malformation (3 papers, 2011 to 2021). "As the hPSCs differentiate toward kidney progenitors in vitro, they expressed the transcription factors PAX2 and SALL1, respectively mutated in the human renal coloboma and Townes-Brocks syndromes featuring kidney malformations." (PMID 29429961, 2018).
acute kidney injury (2 papers, 2023 to 2025). Sudden and sustained deterioration of the kidney function characterized by decreased glomerular filtration rate, increased serum creatinine or oliguria. "Most SALL1 mutations locate in the hotspot mutations region, and renal failure is more likely to occur in patients with these SALL1 mutations." (PMID 37644569, 2023). "However, the homozygous SALL1 mutation (c.3160 C > T) in 2 female siblings with renal failure, multiple congenital anomalies, central nervous system defects, and cortical blindness was reported." (PMID 37644569, 2023). "Group F contained one patient with severe renal failure caused by a splice mutation in SALL1 (c." (PMID 37644569, 2023).
acute myeloid leukemia (2 papers, 2018 to 2021). Acute myeloid leukemia (AML) is a group of neoplasms arising from precursor cells committed to the myeloid cell-line differentiation. "Furthermore, SALL1 seems to have an oncogenic role in acute myeloid leukemia (AML)." (PMID 34944911, 2021). "We examined the expression and functional characterization of SALL1 in NBM and in acute myeloid leukemia (AML) using in vitro and in vivo assays." (PMID 29484122, 2018).
asthma (2 papers, 2021 to 2022). "SALL1 gene expression was upregulated in patients with asthma (βlimma = 0.12, plimma = 0.0173, βballi = 0.12, pballi = 0.0092)." (PMID 35886039, 2022). "LEPN observed in this EWAS is involved in angiogenesis, PTGS1 from isocyanate-asthma research is involved in angiogenesis regulation, and SALL1 and PDZRN3 observed in our GWAS on isocyanate biomarkers are also involved in angiogenesis and vascular morphogenesis, respectively." (PMID 34335698, 2021).
breast tumor (2 papers, 2010 to 2018). "We thus determined whether induction of ATM-associated DNA damage is the main trigger for SALL1-induced senescence in breast tumor cells." (PMID 29625565, 2018). "We determined the activation of mTOR and its downstream substrates p70S6K and 4E-BP1, in breast tumor cells after transfection with SALL1." (PMID 29625565, 2018). "Our studies clearly showed that SALL1 expression in breast tumor cells selectively modulated the MAPK p38 and ERK1/2, as well as mTOR signaling pathways in tumor cells." (PMID 29625565, 2018). "However, over-expression of wild type SALL1 in E0771 cells dramatically inhibited breast tumor progression and growth." (PMID 29625565, 2018). "Furthermore, the numbers and sizes of tumor cell colonies were also significantly increased in three breast tumor cell lines after knockdown of SALL1 in a colony formation assay." (PMID 29625565, 2018). "We therefore measured apoptosis and cell death in SALL1-transfeced breast tumor cells." (PMID 29625565, 2018). "In addition, knockdown of ATM expression with shRNA significantly decreased the senescent cell populations in SALL1-transfected breast tumor cells, further confirming the involvement of the ATM-associated DNA damage response in SALL1-induced tumor cell senescence." (PMID 29625565, 2018). "We next investigated whether over-expression of the SALL1 inhibited breast tumor metastasis." (PMID 29625565, 2018). "We observed that inhibitors U0126 and SB203580 significantly reduced SALL1-induced senescent cell populations in both MCF-7 and E0771 breast tumor cells." (PMID 29625565, 2018). "We observed that over-expression of SALL1 in E0771 and MCF7 breast tumor cells markedly inhibited the migration of tumor cells compared with the tumor cells alone, or tumor cells transfected with mSALL1 or vector." (PMID 29625565, 2018). "Using a combination of COBRA and sequencing of bisulphite modified DNA, we confirmed 5 novel genes frequently methylated in breast tumours; EMILIN2, SALL1, DBC1, FBLN2 and CIDE-A." (PMID 20205715, 2010). "Transfection of SALL1 but not mutated SALL1 in both MCF-7 and E0771 breast tumor cells significantly induced the phosphorylation of mTOR, p70S6K, and 4E-BP1, further confirming the activation of mTOR signaling in tumor cells after SALL1 expression." (PMID 29625565, 2018).
CHARGE syndrome (2 papers, 2017 to 2023). CHARGE syndrome is a multiple congenital anomaly syndrome characterized by the variable combination of multiple anomalies, mainly Coloboma; Choanal atresia/stenosis; Cranial nerve dysfunction; Characteristic ear anomalies (known as the major 4 C's). "The causes were autosomal recessive non-syndromic hearing loss (GJB2), Townes–Brocks syndrome (SALL1), Pendred Syndrome (SLC26A4), Chromosome 8P inverted duplication and deletion syndrome, and CHARGE syndrome (CHD7)." (PMID 36675424, 2023). "Genetic causes included autosomal recessive non-syndromic hearing loss (GJB2/connexin 26), Townes–Brocks syndrome (SALL1), Pendred syndrome (SLC26A4) and Chromosome 8P inverted duplication and deletion syndrome, and CHARGE syndrome (CHD7)." (PMID 36675424, 2023). "Genetic causes for the uSNHL were found in 28% of subjects (5/18) including CHARGE syndrome (CHD7), autosomal recessive non-syndromic hearing loss (GJB2), Townes–Brocks syndrome (SALL1), Pendred Syndrome (SLC26A4) and Chromosome 8P inverted duplication and deletion syndrome." (PMID 36675424, 2023).
cystic kidneys (2 papers, 2009 to 2018). "The in vivo repressive effect(s) of SALL4 were evaluated in SALL4 transgenic mice, where decreased expressions of PTEN and SALL1 were associated with myeloid leukemia and cystic kidneys, respectively." (PMID 19440552, 2009). "The SALL4-mediated repression of the expression of PTEN and SALL1 has been confirmed both in vitro and in vivo and is associated with phenotypes observed in SALL4B transgenic mice, i.e. AML and cystic kidneys, respectively." (PMID 19440552, 2009).
head and neck carcinoma (2 papers, 2021 to 2023). A carcinoma that arises from the head and neck region. "For instance, SALL1 acted as a novel biomarker for the prognosis of early-stage head and neck cancer." (PMID 34178996, 2021). "In this figure, SIX1 represents the SIX family, and there were no data regarding PAX2 and SALL1 in head and neck carcinoma according to the TCGA database." (PMID 36983712, 2023).
head and neck squamous cell carcinoma (2 papers, 2021 to 2024). A squamous cell carcinoma that arises from any of the following anatomic sites: lip and oral cavity, nasal cavity, paranasal sinuses, pharynx, larynx, and salivary glands. "SALL1 promoter hypermethylation was found to correlate with reduced disease-free survival in patients with head and neck squamous-cell carcinoma and is suggested as an important biomarker." (PMID 39654143, 2024). "Several studies indicate that the hypermethylation of SALL1 and SALL3 promoters correlates with poor outcomes and recurrence in head and neck squamous cell carcinoma (HNSCC)." (PMID 34944911, 2021).
leiomyoma (2 papers, 2020 to 2024). A well-circumscribed benign smooth muscle neoplasm characterized by the presence of spindle cells with cigar-shaped nuclei, interlacing fascicles, and a whorled pattern. "Two sequence variants, rs3820282 at WNT4 and rs12325192 near SALL1 also associate with other traits that are strongly affected by estrogen exposure, i.e. leiomyoma (rs3820282 and rs12325192), gestational duration (rs3820282) and endometriosis (rs3820282)." (PMID 32184442, 2020). "Two POP variants associate with conditions related to estrogen exposure, rs3820282 at the WNT4 locus (leiomyoma of uterus, gestational duration and endometriosis) and rs12325192 at the SALL1 locus (leiomyoma)." (PMID 32184442, 2020).
polycystic kidneys (2 papers, 2023). "Thus, some patients with SALL1 mutations have symptoms similar to ciliopathies such as polycystic kidney disease and hearing loss occur." (PMID 37644569, 2023). "Functional kidney impairment with or without structural abnormalities, including polycystic kidneys, has been reported in 42% of individuals with TBS1, and rare SALL1 variants were detected in 0.5–1.4% of CAKUT patients." (PMID 36066768, 2023).
prostate tumors (2 papers, 2010 to 2017). "Colorectal tumour lines showed frequent methylation of all 5 genes, whilst prostate tumour lines demonstrated frequent methylation of CIDE-A, DBC1, EMILIN2, SALL1 and less frequent methylation for FBLN2." (PMID 20205715, 2010). "SALL1 demonstrated similar frequencies of methylation in tumour and matched normal samples for both NSCLC and prostate tumours." (PMID 20205715, 2010).